KRAS (KRas proto-oncogene, GTPase)
Diseases named in the same sentence as KRAS in open-access papers (continued):
Sharing a sentence is not in itself a finding about the gene and the disease.
non-small cell lung carcinoma (continued). "In non-small cell lung cancer (NSCLC) patients, testing for mutations in EGFR and KRAS, and EML4-anaplastic lymphoma kinase (ALK) gene rearrangements to select appropriately targeted therapy occurs on a routine basis." (PMID 24375389, 2014). "Although oncogenic KRAS mutations are frequent, BRAF mutations (BRAFV600E) are found in 3% of human non-small cell lung cancers." (PMID 23825589, 2013). "The aim of this study was to determine the frequency of EGFR, KRAS, BRAF, and HER-2 mutations in brain metastases from non-small cell lung carcinomas (BM-NSCLC)." (PMID 23930206, 2013). "The compound also exhibits activity in animal models of KRAS-mutant non-small cell lung carcinoma xenografts, and thus potentially represents an effective therapeutic intervention for NSCLC patients with gefitinib- or erlotinib-resistant disease." (PMID 24261963, 2013). "Further, we performed the KRAS-knockdown experiments using Lentivirus-based approach to characterize the lamin pS392 status in three non-small cell lung cancer cells (A549, H322 and H1299) cultured in serum-free condition." (PMID 21637843, 2011). "We performed HRM analysis for EGFR and KRAS on DNA isolated from a panel of 200 non-small cell lung cancer (NSCLC) samples derived from FFPE tissues." (PMID 18495026, 2008). "Additionally, GAs in KRAS, including KRAS G12C mutations, were more frequently seen in KMT2Ar AML, which has more clinical implications in solid malignancies like non-small-cell lung cancer." (PMID 41514668, 2026). "Similarly, loss of the transcription factor GATA-binding factor 2 (GATA2) reduces the viability of newly diagnosed non-small-cell lung cancer (NSCLC) cells harboring KRAS mutations, which drive aberrant KRas signaling." (PMID 40906088, 2025). "Furthermore, non-small cell lung cancer (NSCLC) characterized by mutations in the epidermal growth factor receptor (EGFR) and Kirsten rat sarcoma viral oncogene homolog (KRAS), displays pronounced CD73 expression signatures." (PMID 41188606, 2025). "For instance, trial NCT03819387, a Phase I study for non-small cell lung cancer (NSCLC), employs lipid nanoparticles (LNPs) to deliver siRNA targeting glutathione S-transferase P (GSTP) with the goal of inhibiting tumor growth in KRAS-mutated cancers." (PMID 40386463, 2025). "In non-small cell lung cancer (NSCLC), mutations in the Kirsten rat sarcoma viral oncogene homolog (KRAS) gene are among the most frequent genetic alterations, particularly in smokers, and are associated with aggressive tumor phenotypes and resistance to targeted therapies." (PMID 41333851, 2025). "Notably, the co-occurrence of KRAS and KEAP1 mutations has been linked to poorer clinical outcomes and reduced therapeutic efficacy in non-small cell lung cancer, further supporting a potential cooperative role of KEAP1 alterations and MAPK activation." (PMID 41573641, 2025). "TVB-2640 is a potent and reversible inhibitor of FASN and has been validated in a variety of tumor cell lines, including KRAS-mutant non-small cell lung cancer (NSCLC), colon cancer, advanced HER2 breast cancer, and glioblastoma, as well as in clinical studies." (PMID 39990210, 2025). "Genomic analyses of pre- and post-treatment samples from patients—including those with non-small cell lung cancer, CRC, and appendiceal cancer—revealed secondary KRAS mutations (such as G12D/R/V/W, G13D, Q61H, R68S, H95D/Q/R, or Y96C) and KRAS amplification as contributors to resistance." (PMID 39757310, 2025).
non-small cell lung carcinoma (continued). "Furthermore, context-dependent function is also identified in case of Kirsten rat sarcoma viral oncogene homolog (KRAS)/LKB1 mutant non-small cell lung cancers where overexpression of CPS1 drove de novo pyrimidine biosynthesis pathway dependency." (PMID 40961924, 2025). "Mutational activation of KRAS occurs commonly in lung carcinogenesis and, with the recent U.S. Food and Drug Administration approval of covalent inhibitors of KRASG12C such as sotorasib or adagrasib, KRAS oncoproteins are important pharmacological targets in non-small cell lung cancer (NSCLC)." (PMID 39213022, 2024). "A recent study conducted in over 350 Vietnamese patients with non-small cell lung cancer (NSCLC) from four hospitals revealed the presence of EGFR mutations in 35% of cases, KRAS mutations in 23%, ALK rearrangements in 7%, ROS1 rearrangements in 3%, BRAF mutations in 2%, and NRAS mutations in 0.6%." (PMID 38317094, 2024). "However, it's worth noting that in the context of treating non-small cell lung cancers (NSCLCs) with KRAS inhibitors like ARS1620, a significant challenge arose as these tumors frequently developed resistance during the course of treatment." (PMID 38707537, 2024). "In a Phase I clinical trial encompassing various solid tumors, sotorasib displayed a modest 7% response rate in 42 KRAS G12C mCRC patients, contrasting with the higher response rates (up to 32%) observed in other cancer types such as non-small cell lung cancer (NSCLC)." (PMID 38254903, 2024). "Thus, SLC7A1-mediated arginine uptake becomes a potential therapeutic vulnerability for the treatment of KRAS-mutant non-small cell lung cancer." (PMID 39744129, 2024). "Using a combination of genetically engineered mouse models, loss-of-function RNAi screens in primary tumor cells derived from these models, and 3D cultures of human non-small cell lung cancer cell lines we show that UHRF1 plays a key role in KRAS-driven oncogenesis." (PMID 37407562, 2023). "Recently, sotorasib was approved by the FDA for KRAS G12C mutation in non-small cell lung cancer, but drugs for the treatment of other KRAS mutations are still not available." (PMID 37069612, 2023). "In May 2021, the first-in-class KRasG12C inhibitor Sotorasib (Amgen) was approved by the FDA for the treatment of non-small-cell lung cancer (NSCLC), confirming the therapeutic susceptibility of mutant KRas in cancer." (PMID 36972177, 2023). "In addition, KRAS degradation also mediated tumor regression in the KRAS mutant H358 mouse xenograft model of non-small cell lung cancer." (PMID 37592990, 2023). "Finally, the undruggable became druggable by the successful discovery and FDA approval of KRAS G12C inhibitor sotorasib (AMG 510) for the treatment of non-small-cell lung cancer (NSCLC) and other solid tumors." (PMID 37396909, 2023). "In conclusion, we demonstrate that not all KRAS mutations are equivalent in predicting the efficacy of ICIs in patients with non-small cell lung cancer." (PMID 37954616, 2023). "KRAS is the best-known oncogene with the most frequent mutation rate among all cancers and is considered the most common oncogenic gene driver in human cancers, and it is most commonly seen in CRC, non-small cell lung cancer (NSCLC), and pancreatic cancer." (PMID 36788889, 2023). "However, in a phase I clinical of KRAS mutant non-small cell lung cancer patients, it was found that combination Tra/Pon treatment was associated with cardiovascular (CV) and bleeding toxicities." (PMID 35739276, 2022). "KRAS G12C mutations were detected most frequently in patients with nonsquamous non-small-cell lung cancer (NSCLC; 7.5%)." (PMID 36139444, 2022).
non-small cell lung carcinoma (continued). "Interestingly, in a KRAS-driven non-small cell lung cancer mouse model, ERK-induced concomitant upregulation of Ccnd1, as well as Ccnd3, was observed, rendering the tumor resistant to palbociclib." (PMID 35013097, 2022). "However, the KRAS mutations show uneven prevalence in the pan-cancer studies as KRASG12C and KRASG12V are predominant in non-small cell lung cancer (NCLC) while KRASG12R was more common in pancreatic ductal adenocarcinoma." (PMID 35796805, 2022). "No antiproliferative activity was seen in non-small cell lung cancer and other lung cancer cell lines with and without KRAS mutations." (PMID 33637115, 2021). "Programmed cell death receptor ligand-1 (PD-L1) expression, KRAS (KRASm) and EGFR (EGFRm) mutations may influence non-small cell lung cancer (NSCLC) prognosis." (PMID 34413420, 2021). "There is an ongoing clinical trial evaluating a pan-RAF inhibitor in combination with ERK or MEK inhibitors in KRAS-mutant non-small cell lung cancer and NRAS-mutant melanoma which will hopefully provide insights about RAF-ERK vs RAF-MEK inhibitory combinations (NCT02974725)." (PMID 34805167, 2021). "Finally, statins can overcome the resistance to EGFR tyrosine kinase inhibitors in a non-small cell lung cancer cells and to gefitinib in KRAS-mutant human non-small cell lung cancer cells." (PMID 33718197, 2021). "On the basis of previous findings, they screened the entire genome (16,019 genes) in shRNA-infected KRAS-mutant non-small-cell lung cancer (NSCLC) H23 cells, trying to identify triple combination therapies using ARS-1620, mTOR inhibitors and the IGF1R inhibitor linsitinib." (PMID 34257597, 2021). "One such alteration in non-small cell lung cancer is the Kirsten Rat Sarcoma (KRAS) oncogene." (PMID 34064232, 2021). "Cancer cells are known to resist activation of the cGAS-STING pathway, and it has been reported that silencing of STING or cGAS prevents the induction of antitumor immune responses in colorectal cancer, malignant melanoma, ovarian cancer, and KRAS-mutant non-small-cell lung cancer (NSCLC)." (PMID 34445736, 2021). "In addition, limited single-agent activity of MCL-1 inhibitors can be boosted with rationale combination approaches such as MEK inhibitors in KRAS-mutant non-small-cell lung cancer (NSCLC)." (PMID 33308268, 2020). "Additionally, in non-small cell lung cancer, the oncogenic KRAS can induce the IL-8 overexpression that is directly associated with the production of NETs." (PMID 32228650, 2020). "We believe that the mechanism of high expression of EZH2 on non-small-cell lung cancer may be related to the KRAS and BRAF pathways." (PMID 33299862, 2020). "Rizzo S found that a pleural effusion related to ALK mutations while nodules located in non-tumour lobes or round lesion shapes were related to a KRAS mutation in subgroups of non-small cell lung cancer patients." (PMID 31215432, 2019). "Thus, targeting this new class of Treg-like cells discovered in the present work represents a unique therapeutic approach for KRAS-driven cancers including non-small cell lung cancer." (PMID 31635338, 2019). "This could support the clinical use of FAK/PYK2 inhibitor such as VS-6063 (DEFACTINIB) that is already in phase I trial for solid tumor and in phase II study for patients with KRAS mutant in non-small cell lung cancer." (PMID 29455640, 2018). "However, few studies have prospectively investigated the clinical relevance between the presence of EGFR or KRAS mutations and occurrence of venous thromboembolism(VTE) in patients with non-small cell lung cancer (NSCLC)." (PMID 29743116, 2018). "Mutant KRAS has been suggested to cause radioresistance in non-small cell lung cancer (NSCLC) by promotion of non-homologous end joining, though more research is needed to better establish this connection." (PMID 30197760, 2018).
non-small cell lung carcinoma (continued). "Our results were consistent with a previous work demonstrating that atorvastatin could overcome gefitinib resistance in KRAS mutant human non-small cell lung carcinoma cells." (PMID 29449645, 2018). "Knockdown of oncogenic KRAS was found to suppress tumor growth in non-small cell lung cancers." (PMID 28415592, 2017). "We also analysed recently published data of the site of recurrence of 481 resected non-small cell lung cancers according to KRAS and EGFR mutation status, and found that KRAS mutations overall were highly significantly (P<0.0001; Fischer's exact test) associated with pleural recurrence." (PMID 28508873, 2017). "A phase I/Ib study evaluating trametinib plus docetaxel or pemetrexed in patients with advanced KRAS-mutant non-small cell lung cancer (NSCLC) showed that the primary endpoint of overall response rate (ORR) was met for both combinations (ClinicalTrials.gov number, NCT01192165)." (PMID 28954413, 2017). "For instance, the identification of KRAS mutation at codons 12 and 13 in metastatic CRC predicts the lack of benefit from EGFR-targeted antibodies, and for the non-small cell lung cancer patients with EGFR del746_A750 or L858R, they are very responsive to EGFR tyrosine kinase inhibitors." (PMID 28769798, 2017). "Moreover, this early trial reported an impressive response rate of AKT and MEK combination in KRAS mutant non-small cell lung cancer (NSCLC) patients." (PMID 26821351, 2016). "Furthermore, abrogation of CDK4 was synthetically lethal in KRAS mutant non-small cell lung cancer models." (PMID 27167191, 2016). "Non-small-cell lung cancer (NSCLC) cell lines bearing EGFR, KRAS, BRAF, ALK or RET mutations were found with high level of PD-L1 expression, and this may be correlated with high levels of PI3K/AKT/mTOR pathway activation." (PMID 26919108, 2016). "KRAS mutations in non-small-cell lung cancer (NSCLC) patients are considered a negative predictive factor and indicate poor response to anticancer treatments." (PMID 27283493, 2016). "Initial implementation of this multiplexed SCODA mutation enrichment and detection assay focused on 46 mutations in 4 genes (BRAF, EGFR, KRAS, and PIK3CA), constituting a set of commonly encountered mutations of clinical relevance in colorectal and non-small cell lung cancers." (PMID 25575824, 2015). "Epidermal growth factor receptor (EGFR) mutations, v‐Ki‐ras2 Kirsten rat sarcoma (KRAS) mutations and anaplastic lymphoma kinase (ALK) gene rearrangements represent driver mutations that are frequently assessed on initial evaluation of non-small-cell lung cancer (NSCLC)." (PMID 26555338, 2015). "Although many molecular genetic studies indicate that there are some genetic mutations in non-small cell lung cancer (NSCLC), including EGFR, KRAS, PIK3CA, BRAF, ALK, DDR2, and PDGFRA, only a few studies have focused on the genetic events of salivary gland-type lung carcinomas." (PMID 26575266, 2015). "Expression of NQO1 and clinically relevant proteins in non-small cell lung carcinoma patients with and without KRAS mutations." (PMID 25222473, 2014). "By contrast, for advanced non-small cell lung cancer, the benefit of cetuximab has been shown regardless of KRAS mutation status in a phase III trial of cisplatin and vinorelbine treatment, with or without cetuximab." (PMID 24179496, 2013).
non-small cell lung carcinoma (continued). "Here were have focused on a ‘triple negative’ breast cancer cell type; however, this could easily be substituted for another cell type such as a KRAS-mutant non small cell lung carcinoma cell type." (PMID 23406016, 2013). "However, KRAS mutations, primarily single-base missense mutations occurring at codons 12, 13 or 61, have been found to drive tumourigenesis of pancreatic ductal adenocarcinoma (PDAC), colorectal cancer (CRC) and non-small-cell lung cancer (NSCLC)." (PMID 39820726, 2025). "Moreover, a Phase Ib study suggests that multi-segment blockade of the RAS/RAF/ERK pathway may offer significant antitumor efficacy in patients with advanced and metastatic KRAS or BRAF-mutant non-small cell lung cancer." (PMID 40242250, 2025). "Additionally, USP28-mediated FOXK1 deubiquitination activates the Hippo signaling pathway to regulate cell proliferation and radiosensitivity, while targeting USP47 enhances the efficacy of KRAS G12C inhibitors in mutant non-small cell lung cancer through regulation of c-Myc deubiquitination." (PMID 41488674, 2025). "Similarly, Yu found that in KRAS-mutant non-small cell lung cancer cells, cisplatin treatment increased overall m6A modification levels by regulating the post-translational modifications (PTMs) of ALKBH5, thereby enhancing DNA damage repair capacity and promoting resistance to platinum-based drugs." (PMID 40719884, 2025). "The hotspot mutations (G12, G13, and Q61) of KRAS, overcomes the GTPase activity and promote the proliferation & progression of various cancers including pancreatic ductal adenocarcinoma (PDAC), colorectal adenocarcinoma (CRC), and non-small cell lung cancer (NSCLC) respectively." (PMID 39453574, 2024). "In addition, it has been reported that TMB is not an accurate predictive biomarker for ICIs, for example, non-small cell lung cancer patients with KRAS and SKT11 co-mutations and high TMB do not respond to immunotherapy." (PMID 36923532, 2023). "Interestingly, PDK-1 has been also described to promote tumor cell proliferation and migration in non-small cell lung cancer (NSCLC) by enhancing the Warburg effect 7 and previous works demonstrate tight correlation between abnormal cancer cell metabolism and KRAS mutation in several neoplasias." (PMID 33664850, 2021). "For example, a single nucleotide polymorphism (SNP) within a let-7 target site in KRAS is associated with increased risk for non-small cell lung carcinoma, ovarian cancer and triple negative breast cancer: the variant allele enhances KRAS expression in vitro by reducing let-7-mediated suppression." (PMID 28704519, 2017). "Specifically, JQ1 did not alter MYC transcription in embryonic stem cells (ESCs) or in non-small cell lung carcinoma (NSCLC) harboring alteration in KRAS." (PMID 26111384, 2015). "Recently a single-nucleotide polymorphism (SNP) was detected in a let-7 miRNA complementary site in the KRAS 3′UTR in non-small cell lung carcinoma (NSCLC) and was found to be correlated with increased risk for NSCLC." (PMID 22102901, 2011). "In non-small cell lung cancer, FTO has been demonstrated to enhance tumor proliferation through multiple m6A-dependent mechanisms, including activation of KRAS signaling and upregulation of USP7 and MZF1." (PMID 39773744, 2025). "A carcinoid subtype in which SMARCA4, KRAS, FGF3/4/19, STK11, CDKN2A/B, and other genomic alterations predominate in non-small cell lung cancer-like subtypes." (PMID 40661782, 2025).